FGD2 (FYVE, RhoGEF and PH domain containing 2)
Description:
Activates CDC42, a member of the Ras-like family of Rho- and Rac proteins, by exchanging bound GDP for free GTP. Activates JNK1 via CDC42 but not RAC1. Binds to phosphatidylinositol 4,5-bisphosphate, phosphatidylinositol 3,4,5-trisphosphate, phosphatidylinositol 5-monophosphate, phosphatidylinositol 4-monophosphate and phosphatidylinositol 3-monophosphate (By similarity).
Synonyms: ZFYVE4
Tractability: Antibody: its Gene Ontology location is reachable by antibodies, with medium confidence. PROTAC: its protein half-life has been measured.
Gene: Protein-coding gene on chromosome 6 (37,005,645 to 37,029,299, forward strand). Ensembl gene ENSG00000146192.
Subcellular location: Cytoplasm, cytoskeleton; Cytoplasm; Nucleus; Early endosome; Early endosome membrane; Cell projection, ruffle membrane
Pathways (Reactome):
Signal Transduction: CDC42 GTPase cycle; G alpha (12/13) signalling events; NRAGE signals death through JNK
Gene Ontology:
Molecular function: protein binding; guanyl-nucleotide exchange factor activity; small GTPase binding; metal ion binding; phosphatidylinositol phosphate binding
Biological process: actin cytoskeleton organization; cytoskeleton organization; filopodium assembly; regulation of cell shape; regulation of GTPase activity; regulation of small GTPase mediated signal transduction
Cellular component: cytoplasm; cytosol; Golgi apparatus; lamellipodium; ruffle; cytoskeleton; early endosome; early endosome membrane; nucleus; ruffle membrane
Genetic constraint (gnomAD): Loss-of-function variants: 53 observed, 74.65 expected, observed/expected ratio (o/e) 0.71, 90% interval 0.57 to 0.89. The upper end of that interval is the gene's LOEUF score, 0.89, which puts it in group 3 of 6, group 1 being the genes least tolerant of losing a copy. Missense variants: 790 observed, 878.95 expected, observed/expected ratio (o/e) 0.9, 90% interval 0.85 to 0.95. Synonymous variants: 347 observed, 350.42 expected, observed/expected ratio (o/e) 0.99, 90% interval 0.91 to 1.08.
Homologues: Orthologues: chimpanzee FGD2 (99% identical), macaque FGD2 (96% identical), pig FGD2 (90% identical), dog FGD2 (88% identical), rat Fgd2 (82% identical), mouse Fgd2 (81% identical), rabbit FGD2 (78% identical), guinea pig FGD2 (72% identical), Caenorhabditis elegans exc-5 (25% identical), Caenorhabditis elegans frm-3 (7% identical). Paralogues in human: FGD4 (49% identical), FGD1 (47% identical), FGD3 (37% identical), FGD6 (29% identical), FGD5 (28% identical), FARP2 (22% identical), FARP1 (21% identical), ECT2L (14% identical), ARHGEF39 (13% identical), FRMD7 (5% identical).
Diseases named in the same sentence as FGD2 in open-access papers:
FGD2 is named in the same sentence as 9 diseases in open-access papers, as found by Europe PMC text mining. Sharing a sentence is not in itself a finding about the gene and the disease. The quoted sentences say what the papers report.
faciogenital dysplasia (1 paper, 2019). "FGD2 is an understudied member of the FGD1 family of CDC42 GEFs, and mutations in this family have been associated with faciogenital dysplasia, a disease thought to originate from cellular migration defects during embryonic development." (PMID 31556874, 2019).
nasopharyngeal carcinoma (1 paper, 2017). A carcinoma arising from the nasopharyngeal epithelium. "FGD2, for instance, activates CDC42 and has an important paralog, FGD4, which has been found to interact with EBV LMP1 protein to activate CDC42, a mechanism suggested to be implicated in the nasopharyngeal carcinoma tumurogenesis." (PMID 28654678, 2017).
FGD2 also shares sentences with these, for which no sentence is quoted: cancer (2 papers); tumor (2); head and neck squamous cell carcinoma (1); Obesity (1); restless legs syndrome (1); schizophrenia (1); Tourette syndrome (1).